Y_RNA (Y RNA )
Gene: Miscellaneous RNA gene on chromosome 18 (23,582,016 to 23,582,121, reverse strand). Ensembl gene ENSG00000199366.
Homologues: Orthologues: chimpanzee Y_RNA (97% identical), macaque Y_RNA (92% identical). Paralogues in human: RNY1P5 (86% identical), Y_RNA (85% identical), Y_RNA (84% identical), RNY1P1 (83% identical), Y_RNA (83% identical), RNY1P6 (82% identical), Y_RNA (82% identical), RNY1P14 (81% identical), Y_RNA (81% identical), Y_RNA (80% identical), Y_RNA (79% identical), RNY1 (78% identical), and 94 more.